IL6 (interleukin 6)
Diseases named in the same sentence as IL6 in open-access papers (continued):
Sharing a sentence is not in itself a finding about the gene and the disease.
cancer (continued). "It effectively suppressed the secretion of vascular endothelial growth factor A (VEGF-A) and interleukin 6 (IL-6) from cancer cells." (PMID 38535455, 2024). "Our findings suggest that ASCs differentiate into CAFs within the cancer stroma of PM and that IL-6 secreted by ASCs induces 5-FU resistance through the upregulation of Nanog and CD44v6 in the PM of GC." (PMID 39766174, 2024). "Here, we extend existing general modeling frameworks to build a quantitative, computational model for a specific therapeutic target: antibodies targeting the IL-6 and IL-8 receptors for the prevention of cancer metastasis." (PMID 38848446, 2024). "For example, IL6 is a glycosylated multifunctional cytokine that influences cancer cell activity and differentiation and immunomodulation of the microenvironment as an essential mediator of the acute inflammatory response." (PMID 39432122, 2024). "Considering its multiple effects, IL-6 has emerged as a potential therapeutic target in cancer treatment." (PMID 38338683, 2024). "In OC, IL6 via JAK/STAT promotes the expression of CD44, also known as Homing Cell Adhesion Molecule (HCAM), a transmembrane glycoprotein associated with cancer cell stemness." (PMID 39766086, 2024). "IL-6 is also a key player in paraneoplastic syndromes, further emphasizing its role in cancer progression." (PMID 39594709, 2024). "These examples highlight the potential of using antibodies to target specific SASP components like IL-6 and IL-8 as a strategy to modulate the effects of senescent cells in cancer therapy." (PMID 38913050, 2024). "In aspects of cancer, neutrophils are elevated by immunosuppressive mediators, primarily IL-6 derived from tumors." (PMID 39464714, 2024). "At this time, Schwann cells were activated by interleukin-6 (IL-6) produced by cancer cells, facilitated PNI, which was accompanied by changes in hypoxia-related signaling pathways, such as HIF1α." (PMID 39119085, 2024). "The most prominent cytokines in our series, common to all cancers, are IL-6 and its soluble receptor IL-6Rα, TGFβ, IL-10, and G-CSF." (PMID 39114667, 2024). "The role of inflammation in cancer progression, particularly the involvement of pro-inflammatory cytokines such as IL6, was widely accepted based on Virchow’s proposal." (PMID 39766086, 2024). "In turn, THP-1-derived macrophages stimulate the EMT process and then the invasion and metastasis of cancer cells through the secretion of IL-6." (PMID 39057050, 2024). "Second, pro-survival signaling amidst CIN leads to an increase of other factors (such as IL6) that induce a pro-cancer, M2-like phenotype." (PMID 37066426, 2024). "Certain proinflammatory cytokines, including IL‐1, IL‐3, and IL‐6, induce thrombopoiesis in cancer patients." (PMID 39102040, 2024). "Our study identifies AP neurons as a critical mediator of the function of IL-6 that leads to cancer cachexia in mice." (PMID 38824130, 2024). "Increased energy provision by OXPHOS results in increased IL-6 production, leading to the longer survival and increased proliferation of cancer cells." (PMID 38191325, 2024). "Although IL-6/IL-6R-inhibiting compounds are in clinical development for various cancers, there is evidence that vaccination-based immunotherapy depends on IL-6 signaling in TAMs for optimal treatment efficacy." (PMID 39500527, 2024). "IL-6, involved in the pathophysiology of inflammation, auto-immunity and cancer, plays an important role in myocardial remodelling since it promotes transforming growth factor-β mediated fibrosis." (PMID 39708201, 2024). "IL6ST is a signal transducer through which cytokines, such as IL6, perform pleiotropic functions in many cancer-related processes including inflammatory pathways." (PMID 38987822, 2024). "IL-6 stimulates systemic immune responses and creates an immune suppression environment that protects cancer cells and plays a role in various cancers, including solid tumors and hematomas." (PMID 39120359, 2024).
cancer (continued). "Elevation of IL-6 during cancer progression has been shown to drive cancer cachexia, however, while brain dysfunction has been reported, the underlying mechanism is unclear." (PMID 38824130, 2024). "Adipokines released by adipocytes, such as IL-6 and leptin, are crucial for the promotion of chemotherapeutic resistance in cancer cells." (PMID 38302980, 2024). "We first measured the expression of genes involved in adipocyte differentiation (PPAR-γ, AP2, HSL, Adiponectin, Leptin), cancer-associated fibroblast (CAF) markers (LIF, FAP, α-SMA), and inflammation (IL-6, IL-8, IL-1β, CXCL-10, TNF-α)." (PMID 39072314, 2024). "On the other hand, the level of IL-6, a key factor in chronic inflammatory diseases, autoimmunity, cytokine storm, and cancer, increased only moderately during aging of the Klf1(K74R) mice." (PMID 38752723, 2024). "IL-6 and IL-8 are important cytokines that increase cancer cell activity in many cancers and are involved in tumorigenesis and metastasis." (PMID 39272982, 2024). "Cancer-derived SPP1 is linked to MDSC (myeloid-derived suppressor cells) immunosuppression by regulating arginase 1, NOS2, VEGF, and IL-6." (PMID 38491408, 2024). "IL-6 contributes to cancer chemoresistance by activating signaling cascades that promote cell survival and proliferation." (PMID 39336151, 2024). "In our study, celecoxib effectively reduced serum IL-6 levels and NF-κB but was less effective in suppressing cancer cachexia." (PMID 39624846, 2024). "IL-6 is also a key mediator in cancer-related conditions such as anemia and anorexia, which significantly impair the nutritional intake of essential substrates and microelements like glucose, iron, and zinc." (PMID 39015563, 2024). "The ability of IL-6 to trigger the EMT has been observed in many types of cancers including breast, liver, colon, head and neck and laryngeal squamous carcinoma." (PMID 38473317, 2024). "IL-6 and IL-17 are paradoxical cytokines that progress inflammatory states in chronic diseases, including cancer." (PMID 38279220, 2024). "We identified IL-6 as a novel target of ERO1α and confirmed the suggestion by previous studies conducted using other cancer cell models that STAT3 directly transcriptional regulates SLC7A11." (PMID 38610018, 2024). "This prospective analysis revealed a shift towards immature forms of neutrophils and higher IL-6 levels in patients with cancer and severe COVID-19 infection." (PMID 39272832, 2024). "Elevated levels of IL-6 have been reported in PLWH, even when virally suppressed, and have been associated with comorbidities of HIV such as CVDs and cancer." (PMID 39339938, 2024). "This article systematically highlights how targeting IL6 improves OC outcomes by altering various cancer processes and reports the ongoing clinical trials that would further shape the IL6-based targeted therapies." (PMID 39766086, 2024). "In contrast, antibodies directed against IL-6IF described here selectively block pathological IL-6 synthesis related to enhanced proteolytic activity in diseases such as cancer." (PMID 39518029, 2024). "These encouraging results provided a rationale for conducting pre-clinical and clinical trials that explore the combination of anti-IL6 monoclonal antibodies with existing chemotherapies for various types of cancers." (PMID 39766086, 2024). "In conclusion, our current findings reveal an important mechanism that discloses the role of TAMs on cancer cells through the IL6-STAT3-C/EBPβ-IL6 positive feedback loop in the TME." (PMID 38424624, 2024). "REST (RE1 silencing transcription factor) and RB1 expressions are both downregulated by Interleukin 6 in cancer cells." (PMID 39480826, 2024). "The coculturing of adipocytes with BCa cells resulted in an increased expression and secretion of IL-6 in adipocytes that promoted the invasion and migration of cancer cells." (PMID 39040042, 2024).
cancer (continued). "Although associations have been identified between IL-4, IL-6, IL-8, IL-10, IL-1β, TNF-α, COMT, CLOCK, PER, and 5-HTTLPR-related genes and cancer-related fatigue, the relationship between IL-6 and cancer-related fatigue remains controversial." (PMID 39372868, 2024). "A crucial immunomodulatory cytokine, interleukin-6 (IL-6), influences the etiology of several illnesses, such as cancer, autoimmune disorders, and chronic inflammatory ailments." (PMID 38882664, 2024). "IL-6: IL-6 promotes oncogenic signaling pathways and immune escape, facilitating cancer progression." (PMID 39125732, 2024). "IL-6 exerts various other pro-cancer effects, being involved in angiogenesis and acting as a growth factor for various types of cancer cells, including prostate cancer cells, breast cancer cells, esophageal adenocarcinoma cells, and others." (PMID 39206193, 2024). "So, to check the activity of DiMeOC-Mg-BCD on cancer cell lines at the molecular level, the IL-6/STAT3 signaling pathway was investigated." (PMID 38673967, 2024). "Here we show that neurons in the area postrema (AP), a circumventricular structure in the hindbrain, is a critical mediator of IL-6 function in cancer cachexia in male mice." (PMID 38824130, 2024). "Further studies with a larger sample size and a prospective study design are needed to validate the prognostic role of IL-6 in the context of cancer cachexia in PDAC patients." (PMID 38539528, 2024). "Further analysis showed that inflammatory cytokines (CCL5 and IL-6) derived from the TME are involved in EMT in cancer cells via the STAT3 signaling pathway." (PMID 39126553, 2024). "Treatment with a novel Fc-VEGF chimeric antibody drug (Fc-VFD) inhibits the secretion of pro-angiogenic factors VEGF-A and IL-6 by cancer cells in TME, suppressing excessive angiogenesis and overcoming hypoxia resistance in cancer cells." (PMID 38433193, 2024). "IL-6, TNF-α, and IL-8 from CAFs influence adipose tissue loss, organ fibrosis, and appetite reduction, associated with cancer wasting and cachexia." (PMID 39676864, 2024). "Several studies have examined the prognostic value of IL-6 in cancer therapy, yet its relationship with biomarkers such as GDF-15 has not been fully explored." (PMID 39766045, 2024). "Interleukin-6 (IL-6) is a crucial component of the cancer microenvironment, and a close relationship has been suggested to exist between cancer and PD." (PMID 38396821, 2024). "IL-6 is upregulated in various preclinical models of neuropathic pain, including peripheral injury, cancer pain, and diabetic peripheral neuropathy." (PMID 38001018, 2024). "Our study results suggest a robust association between the P3H score and various cancerous pathways in pan-cancer, including IL6-JAK-STAT3 signaling, IL2 STAT5 SIGNALING response, and the inflammatory response." (PMID 38706607, 2024). "These pathways are IL6-activated, and various studies highlight Quercetin’s inhibitory effect on IL6 and subsequent aid in various cancers." (PMID 39766086, 2024). "The PPM along with Quercetin as reference was used to assess the cytotoxic effect on THP-1 cells and describe its effect on pro-inflammatory cytokines such as COX-2, TNF-α, IL-6 against cancer cell line by flow cytometry." (PMID 40190537, 2024). "The regulation and inhibition of the IL-6/JAK2/STAT3 pathway is conducive to cancer prevention and treatment as well as improved prognosis and, therefore, represents an important target for designing anti-cancer drugs." (PMID 38715108, 2024). "It has been demonstrated that significantly elevated levels of IL-6, IL-8, and IL-10 are exhibited in cancers." (PMID 38337827, 2024). "In cancer patients, low circulating HGF, low IL-6, and high CCR were associated with improved PFS and OS." (PMID 38776028, 2024). "IL-6 has been documented to enhance the chemoresistant properties of several types of cancers, for example through its ability to induce the phosphorylation of BECN1 and to control autophagic activity." (PMID 38440120, 2024).
cancer (continued). "The induction of signal transducer and activator of transcription proteins (STAT) signaling through cytokines such as interleukin-6 (IL-6) is recognized to augment cancer cell proliferation, enhance survival, and promote invasion." (PMID 38254789, 2024). "Elevated levels of certain cytokines, such as interleukin-6 (IL-6) and C-reactive protein (CRP), have been linked to poorer outcomes in cancer patients receiving immunotherapy." (PMID 39335659, 2024). "PD-1 blockade promotes a Th1/Th17 response via enhanced production of interferon γ, interleukin (IL)-2, tumor necrosis factor-α, IL-6, and IL-17 and reduction of Th2 cytokine profiles in patients with cancer." (PMID 39823053, 2024). "The ubiquitous role of IL-6 in immune disorders, inflammatory diseases, and even cancer has prompted the development of various studies with anti-IL-6 antibodies." (PMID 38921397, 2024). "A recently described phenotype of cancer-associated adipocytes (CAAs) (characterized by the production of CCL5, CCL2, IL-6, and TNF-α) has been shown to promote the proliferation and invasion of tumor cells, as well as neovascularization." (PMID 38667297, 2024). "IL-6, acknowledged for its versatile cytokine functions, emerged as a pivotal player in cancer-related processes." (PMID 39015563, 2024). "Telomere length, which tends to shorten with repetitive cellular division in cancer cells, has been found to have an inverse relationship with IL6 levels in OC." (PMID 39766086, 2024). "It is known that Il1b and Il6 expression depends on NF-κB activity, and IL-6 plays an important role in the processes of invasive growth and metastasis of malignant tumors." (PMID 39063041, 2024). "IL-6 is a major pro-inflammatory cytokine involved in the inflammatory response and cancer progression." (PMID 39317690, 2024). "The levels of circulating PD-L1, CXCL10, MIG, HGF, CCL-2, and IL-6 were significantly higher in the cancer group compared with those of the control group." (PMID 38776028, 2024). "In vitro experiments revealed that stress hormones downregulated HDC expression, consequently promoting cancer cell proliferation, migration, and invasion via the IL-6/STAT3/S100A9 pathway." (PMID 39720595, 2024). "For instance, IL-6 derived from M2 macrophages has been found to downregulate the epithelial marker E-cadherin and upregulate the mesenchymal marker vimentin in cancer cells." (PMID 38840908, 2024). "IL-6 re-leased during this process has been shown to regulate the expression of almost all cancer biomarkers and various cancer-related signaling pathways." (PMID 39010072, 2024). "Unphosphorylated STAT2 bridges the interferon-stimulated response and NF-κB elements in the IL-6 promoter and increases cancer cell survival by enhancing IL-6 expression." (PMID 38835896, 2024). "CAFs have been observed in multiple cancer types and are known to secrete factors (e.g., IL6, IL8, TGFB1) that can regulate cancer proliferation and metastasis." (PMID 38281962, 2024). "Long‐chain N‐3 fatty acids have reduced inflammatory cytokines such as IL‐6 or C‐reactive protein and resting energy expenditure in cancer patients." (PMID 39229565, 2024). "Therapeutic strategies for cancer by inhibiting IL-6 trans-signaling should consider the effects of other IL-6 family members." (PMID 38182653, 2024). "The main pro-inflammatory interleukins, such as IL-1 and IL-6, play a crucial role in promoting the development and activation of osteoclasts, supporting the survival of cancer cells, and initiating the growth of new blood vessels in the bone microenvironment." (PMID 39125732, 2024). "Here, the authors identify neurons in the area postrema as a mediator of peripheral IL-6 in preclinical models of cancer cachexia." (PMID 38824130, 2024). "Specifically, chronic stress downregulated HDC expression, reducing HIS production and triggering excessive IL-6 secretion in cancer cells." (PMID 39720595, 2024).
cancer (continued). "Numerous studies have reported that elevated systemic inflammation signified by increased levels of IL‐6, TNF‐α, and CRP contributes to cancer cachexia and is associated with poor survival." (PMID 38725139, 2024). "Targeting STAT3 with Resveratrol, for example, blocks the downstream effects of IL6 and has shown potential in overcoming therapy-induced resistance in OC and various other cancers." (PMID 39766086, 2024). "Localization of IL-6 in cancer tissue was predominantly found in the stroma, especially in cancer-associated fibroblasts, rather than in cancer cells." (PMID 38510850, 2024). "As elevated serum IL-6, IL-8, and IL-11 levels correlate to worse survival in cancer patients, we sought to measure IL-8 in both the serum and plasma samples in the NSCLC patients compared against normal volunteers." (PMID 39329890, 2024). "Pathway analysis implicated genes related to oxidative reduction and lipid metabolism were over-expressed, and genes involved in cancer immunity and interferon signaling were under-expressed in the group with high serum IL-6 levels (respectively)." (PMID 38510850, 2024). "Effectively, IL-6 inhibitors (such as tocilizumab and siltuximab) have shown potential clinical benefit in many cancer subtypes." (PMID 38799450, 2024). "PAR2 activation promotes the release of vascular endothelial growth factor, interleukin-6, and interleukin-8, thereby promoting the formation and invasion of new blood vessels in malignant tumors." (PMID 38172304, 2024). "In prostate cancer, the development of malignant tumors is closely associated with the simultaneous enrichment of YY1 and H3K27ac ChIP-seq signals in the specific enhancer of the IL-6 gene in M2 macrophages." (PMID 38586584, 2024). "Elevated levels of IL-6 have been observed in patients affected by different types of cancer, including pancreatic, breast, prostate, colorectal, and NSCLC." (PMID 39770330, 2024). "This systemic manifestation of cancer is attributed to circulaing cytokines, IL-6 being central among them." (PMID 38689325, 2024). "Clinically, high IL-6 levels are observed in patients suffering from many cancer types, including breast, colon, or pancreatic cancer, to name only a few." (PMID 39201656, 2024). "It is important to highlight that IL-1β, IL-6, IL-8, and TNF-α are directly implicated in cancer development/progression." (PMID 38612423, 2024). "In prostate cancer, breast cancer, ovarian cancer, non-small cell lung cancer, and endometrial cancer, IL-6 also had a correlation with clinical progression of the cancer." (PMID 38800384, 2024). "While studies have shown that the NF-κB signaling pathway is involved in the overexpression of IL-6 in cancer cells, the role of NF-κB in IL-6 overexpression/secretion through miRNA modulation has not been thoroughly investigated." (PMID 38338683, 2024). "The presented anticancer mechanism of desloratadine also included a strong anti-inflammatory effect by inhibiting the release of interleukin-6 from mast cells and basophils, which significantly reduced the migration and invasion of cancer cells." (PMID 39766152, 2024). "IL-6 class cytokines (e.g., IL-6, LIF, OSM, IL-11) are among the few regarded as master regulators of inflammation associated with cancer." (PMID 38384463, 2024). "Increased vascular permeability, driven by cytokines such as IL-6 and tumor necrosis factor-α, facilitates the infiltration of cancer cells into lymphatic and blood vessels." (PMID 39156325, 2024). "Apart from its role in progressing cancer inflammation, IL-6 and IL-17 play a critical role in providing the host with a protective immune response against pathogens." (PMID 38279220, 2024). "Infiltration is more pronounced during episodes of fresh hemorrhage, as only fresh hemoglobin stimulates increases in IL-6, which is essential in cancer." (PMID 38337827, 2024).